BCL2 (BCL2 apoptosis regulator)
Diseases named in the same sentence as BCL2 in open-access papers (continued):
Sharing a sentence is not in itself a finding about the gene and the disease.
tumor (continued). "Despite the fact that bcl-2 does not act directly on cell proliferation, its overexpression enables tumors to progress to highly malignant phenotypes and to become more resistant to chemotherapy and apoptosis-inducing radiation therapy, with subsequent metastatic spread and tumor progression." (PMID 18570663, 2008). "However, it is not known whether Bcl-2 or other apoptotic regulators can influence the levels of thioredoxin or whether such modulation may contribute to resistance in human tumor cells." (PMID 19061505, 2008). "Tumor cells express immunoglobulin light chain and are positive for CD20, CD10, BCL6, and BCL2 but negative for CD5 and CD23 immunohistochemical markers." (PMID 40805131, 2025). "The first-line markers for diagnosing these tumors are bcl-2 and CD34; a tumor that tests negative for both markers is unlikely to be SFT." (PMID 40709355, 2025). "Immunohistochemically, the tumor was positive for vimentin, EMA, PgR, TTF-1, and somatostatin receptors-2, and negative for cytokeratin, Bcl-2, CD34, and S-100, with a Ki-67 index of approximately 5%." (PMID 40265140, 2025). "Morphologically, the tumor comprised a subset of lymphoid cells with centrocytic morphology that was positive for CD20, PAX5, CD10, BCL6, and CD23, and negative for CD5 and BCL2." (PMID 40861583, 2025). "Although establishing a direct link between EV-miRNAs and MM tumor niches in the BM is not possible, isomiRs in our classification signatures target MYC or BCL2 oncogenes driving myelomagenesis." (PMID 40961943, 2025). "These cells tested positive for CD10, CD79a, PAX-5, BCL-2, BCL-6 (10-20%), and c-MYC, but most tumor cells were negative for CD20 on immunohistochemistry." (PMID 41142614, 2025). "However, given the large differences between CPs’ direct binding affinities to BCL-2/BCL-XL proteins and their cellular activities, we could not fully rule out the possibility that certain off-target effects are also involved in the inhibition by CPs on these tumor cells." (PMID 38368459, 2024). "Axl gene expression did not correlate with age, tumor size, LN involvement, ER, PR, HER2, Ki-67, BCL-2, and the biological subtype." (PMID 39463509, 2024). "Immunohistochemical analysis showed the positivity of the tumor to CD20, CD5, Bcl2, and cyclin D1, while it was negative to CD10 and CD23." (PMID 38698463, 2024). "Histopathology revealed a cellular tumor comprising tightly packed round to fusiform cells arranged around blood vessels with intervening thick collagen, positive for CD99, vimentin, BCL2, CD34, and STAT6 and negative for EMA, CK AE1/AE3, S100, TLE1, and SMA." (PMID 38606238, 2024). "MYC amplification was further detected in circulation tumor DNA by next generation sequence in P2 and P8, without MYC or BCL-2 translocation." (PMID 38246951, 2024). "However, the PGE2 addition to Regorafenib treated HMEG cells could not further increase the Bcl-2 expression in tumor cells, indicating that the Regorafenib-induced Bcl-2-upregulation seen in the tumor cells represents a COX2-PGE2 independent tumor cell-autonomous resistance mechanism." (PMID 37620408, 2023). "Furthermore, PTX-TTHA could inhibit tumor proliferation by downregulating Ki-67, and induce apoptosis by increasing pro-apoptotic proteins (Bax, cleaved caspase-3) and TdT-mediated dUTP nick end labeling (TUNEL) positive apoptotic cells, and reducing anti-apoptotic protein (Bcl-2)." (PMID 37175072, 2023). "The tumor cells were negative for MYC and BCL2 rearrangements but positive for BCL6 rearrangement by fluorescent in situ hybridization." (PMID 37884941, 2023). "The tumor cells expressed SATB2, Bcl-2, TLE1, SMARCB1, but not CK, EMA, CD34, SMA, Desmin, S-100, CD99, STAT6, MyoD1, Myogenin, and Ki-67 LI is about 10%." (PMID 37361584, 2023).
tumor (continued). "Our studies concluded that miR-182 is a tumor-suppressor gene and inhibits the self-renewal of LSC but not HSPC via targeting BCL2 and HOXA9, suggesting that miR-182 is potential therapy target for LSC." (PMID 36593968, 2023). "We must also integrate the “non-apoptotic” role of Bcl-xL, namely its mechanism of action for tumor survival, non-related with BH3 and Bcl-2 directly, which should be referred to." (PMID 37720343, 2023). "Immunohistochemical staining showed that the tumor cells were positive for vimentin and Bcl-2 but negative for S-100, desmin Syn, WT-1, EMA, CD34, and CD99; the Ki-67 index in tumor cells was 40%." (PMID 36482604, 2022). "Moreover, the binding of these compounds with some other G-quadruplex DNA, Bcl-2, kras, VEGF, c-kit1 and telomeric may also have occurred, since it is difficult to distinguish different G-quadruplex DNAs that originate from different tumor cells, and this will be investigated in our future studies." (PMID 35335261, 2022). "The scarcity of tumor cells in tumor biopsies did not enable the performance of molecular analysis, especially to investigate MYC, BCL2, or BCL6 rearrangement." (PMID 35538643, 2022). "Besides, the conjugate showed a high antitumor effect in SGC-7901 tumor model with a tumor inhibition rate of 59.57%, and which might be mediated by increasing the levles of TNF-α, Bax and Caspase-3 and reducing the levels of CD34, VEGF, MMP-2, MMP-9 and Bcl-2." (PMID 36463199, 2022). "The tumor cells are positive for CD45, CD30, CD15, MUMi, and Ki-67 (80%) and negative for CD20, PAX-5, CD79a, CD3, CD5, CD10, BCL6, BCL2, EMA, ALK-1, and CD138." (PMID 34900354, 2021). "In the undiluted tumor samples not more than 75 K on-target reads were needed to robustly detect the MYC, BCL2, and BCL6 rearrangements." (PMID 34099699, 2021). "Immunohistochemical staining indicated the tumour was positive for CD34, STAT6, vimentin and bcl-2, but negative for cytokeratins, D2-40 and S-100." (PMID 33623662, 2021). "Immunohistochemistry (IHC) showed that these tumour tissues highly expressed Ki67 and Bcl2 under HBO, but there were no expression of Ki67 and Bcl2 in the control group." (PMID 33986256, 2021). "Using Spearman’s correlation coefficient showed that significant negative correlation was found between miR-148a and Bcl-2, also there was a significant negative correlation between miR-148a with CEA, tumor size and stage." (PMID 34181356, 2021). "Immunohistochemical analysis of the left pleural biopsy specimens suggested DLBCL, where the tumor cells were positive for CD20, PAX5, and BCL-2 but negative for CD10, BCL-6, Mum-1, and LMP-1." (PMID 33564306, 2021). "Immunohistochemical staining is required for the diagnosis of SFTP; the tumor cells are positive for STAT6, CD34, CD99, and BCL2, whereas they are negative for desmin, S-100, and alpha-SMA." (PMID 32638177, 2020). "5-Aza-CdR interestingly decreased levels of genes that promote tumor progression, such as CCND1, MKI67, BIRC5, and BCL2, but failed to decrease MUC4 and NOTCH1." (PMID 32182826, 2020). "For the final diagnosis, immunohistochemistry (IHC) was performed, and the tumor cells tested positive for MPO, CD4, BCL-2, KI-67, and CD117 and negative for CD3, CD5, CD20, CD56, bcl-6, Mum-1, CD123, MUM-1, TdT, Syn, SOX11, and C-myc." (PMID 33120806, 2020).
tumor (continued). "On immunostaining, the tumor was positive for vimentin, CD34, and Bcl-2, and negative for α-smooth muscle actin (α-SMA)." (PMID 31848901, 2020). "In the present case, the pathomorphological examination was nonspecific, but IHC showed positive for EBER, MPO, CD4, BCL-2, CD117, which hinted that tumor cells were from the myeloid cells." (PMID 33120806, 2020). "Immunohistochemical analysis showed that the tumor cells were positive for CD20, BCL2, BCL6, and MUM-1 and were negative for CD5 and CD10." (PMID 33071959, 2020). "Pertinently, the sensitivity of some tumor cell lines to BH3 mimetic ABT737, which targets BCL-2, BCL-XL, and BCL-W but not MCL-1, is enhanced by 2-deoxyglucose (2DG)." (PMID 30538285, 2019). "Immunohistochemistry demonstrated that the tumor cells were positive for CD34, STAT6, vimentin, and Bcl-2, and negative for α-SMA, S100, and EMA." (PMID 31687030, 2019). "The combined status of Cx43 and Bcl-2 did not correlate with DSS (p > 0.05), tumor localization (p = 0.904), tumor size (p = 0.687), stage (p = 0.924), lymph node metastasis (p = 0.43) or response to neoadjuvant chemotherapy (p > 0.05)." (PMID 31766723, 2019). "The Bcl-2 status did not correlate with DSS (p = 0.21), tumor localization (p = 0.531), tumor size (p = 0.136), stage (p= 0.748), lymph node metastasis (p = 0.111) or response to neoadjuvant chemotherapy (p = 0.544)." (PMID 31766723, 2019). "While MCL1, BCL2L1, or BCL2L2 were ubiquitously expressed, BCL2 and BCL2A1 demonstrated tissue/lineage-selective expression with very low/no expression across most of the cancer cell lines and TCGA tumor tissues." (PMID 30635584, 2019). "Immunohistologic analysis demonstrated the tumor cells were positive for α-smooth muscle actin, β-catenin and Vimentin, and negative for AE1/AE3, Bcl-2, CD34, CD117, Factor VIIIR Ag, S-100 protein, or STAT6." (PMID 30206803, 2019). "Tumor cells were not stained for STAT6, AE1/AE3, Bcl-2, CD34, CD117, Factor VIIIR Ag, or S-100 protein (data not shown)." (PMID 30206803, 2019). "In conclusion, there was no change in BAX or Bcl-2 gene and protein expression in response to ECT at the time points evaluated, but ECT was able to reduce tumor volume and cellular proliferation in cSCC." (PMID 31676831, 2019). "Immunohistochemical analysis showed that the tumour was positive for vimentin, CD99, Bcl-2 and CD34 and negative for D2–40, desmin, S-100, SMA and CK and the Ki-67 index was as low as 1%." (PMID 31391089, 2019). "Tumor cells exhibit no strong diffuse staining for CD34 and are basically negative for AE1/AE3, Bcl-2, CD34, CD99, CD117, Factor VIIIR Ag, S-100 protein, and STAT6." (PMID 30206803, 2019). "Based on immunohistochemical examination, the tumour cells were positive for CD34, Bcl2, vimentin, and CD99 and negative for desmin and S-100." (PMID 31391089, 2019). "While compounds selective for BCL-2 over BCL-X have shown anti-tumor effects in vivo with limited platelet toxicities, not all cancers express BCL-2 or require BCL-2 for their continued survival." (PMID 30671383, 2018). "Interestingly, a significant increase in BCL-2/MCL-1 was displayed by HCC samples, that was not presented by the neighboring cirrhotic tissue, suggesting that this modification could be associated to tumor development." (PMID 29682179, 2018). "The tumor cells showed strong and diffuse nuclear immunostaining with beta catenin and were negative with STAT6, CD34 and bcl-2." (PMID 29168109, 2018). "The results of additional immunohistochemical studies (BCL2, MYC, Ki67) showed no impact on CD52 expression status, and tumor morphology (blastoid vs. DLBCL vs. DLBCL/BL) was similarly non-predictive." (PMID 30020951, 2018). "The CMT cells were positive for the epithelial marker, cytokeratin-8; tumor markers, VEGF, HER-2, MMP-2, HIF-1α, and Bcl-2; and hormone receptors, PGR and EPOR, while negative they were for estrogen receptor, ER." (PMID 30410940, 2018).
tumor (continued). "IHC was mainly positive for tumor markers like CD10, CD20, CD45, CD 79a, PAX5, MUM1, and BCL6, and negative for BCL2, ALK, CD30, and cyclin D1." (PMID 30764662, 2018). "In many cancers, high levels of anti-apoptotic proteins such as BCL-2 and BCL-XL were shown to contribute not only to tumor initiation and progression, but also to lack of response to chemotherapy." (PMID 29747654, 2018). "On immunohistochemistry, the tumor was positive for CD34 and CD99 and negative for α-SMA, S-100, and bcl-2." (PMID 28326216, 2017). "Because the tumor cells were positive for CD99 and BCL-2, which are usually negative in a case of malignant mesothelioma, malignant sarcomatoid mesothelioma seemed to be less of a possibility." (PMID 28205183, 2017). "Immunohistochemical staining revealed that the large-sized tumor cells were positive for CD20, PAX-5, MUM-1 and BCL-2, and were negative for CD3, CD5, CD43, CD10, CD23, CyclinD1, CD138, CD30, ALK, CD56, MPO, S-100, TTF-1, thyroglobulin and calcitonin." (PMID 28841887, 2017). "A significant reduction in tumor size was noted in patients with HER2-positive, Tau-negative, Bcl-2-negative and high Ki67 index (p<0.01, p=0.01, p=0.008, and p=0.01, respectively)." (PMID 29254147, 2017). "In vivo experiments demonstrated a superior effectiveness of the combinatorial approach PSPG/DOX/Bcl-2 when compared to PSPG/DOX or PSPG/Bcl-2 alone, with no increase in tumor volume after 22 days of treatment and no side effects." (PMID 28832535, 2017). "In this case, the immunohistochemical findings were compatible with SFT, as the tumor cells were positive for CD34 and bcl-2, whereas alpha-SMA, desmin, and S-100 were negative." (PMID 28063145, 2017). "In conclusion, Bcl-2 negative, HER2-positive and smaller (≤2 cm) tumor sizes are independent predictors of pCR in ER-positive patients treated with dose-dense (biweekly) paclitaxel/carboplatin NCT." (PMID 29254147, 2017). "Compared to the BPDCN groups, non-BPDCN-type CD56+ neoplasm cases showed higher cytoplasmic CD3 positivity and less frequent BCL-2 expression, and absence of cutaneous lesions." (PMID 29225711, 2017). "IHC showed that these tumor cells were diffusely positive for vimentin, focally positive for cytokeratin and EMA, and negative for S-100, bcl-2, and c-kit." (PMID 27068820, 2016). "In type I but not type 2 tumour cells, TRAIL-induced apoptosis is also regulated by the equilibrium between pro-apoptotic BH-3 only and anti-apoptotic B-cell lymphoma-2 (Bcl-2) proteins that regulate mitochondrial outer membrane permeability." (PMID 27821809, 2016). "The quantitative PCR analysis showed that neither Bcl-2 nor Bax expression levels were affected by the presence of tumor cell-derived exosomes, indicating that the decrease in osteoclast formation seen with tumor cell exosome-treated RAW264.7 cells could not be explained by induction of apoptosis." (PMID 27832183, 2016). "Inhibitory effects of C12 on tumor growth are likely attributed to apoptosis, as more TUNEL-positive cells were detected in C12-treated tumors than vehicle-treated ones regardless of Bcl-2 expression levels." (PMID 26758417, 2016). "While both BCL2 transcript and protein are slightly higher in TLK2-high tumours, such differences are not statistically significant." (PMID 27694828, 2016). "Overall, our results demonstrate that C12 inhibits tumor growth independent of both pro- and anti-apoptotic Bcl-2 proteins, and through inducing unique apoptotic signaling mediated by PON2 in tumor cells." (PMID 26758417, 2016). "His immunohistochemistry analysis showed that the tumor cells were positive for vimentin, CD34, BCL-2 and beta-catenin, and negative for pan Cytokeratin, p63, Calretinin, SMA, desmin, S100, CD-31, CD-117, DOG1, EMA, STAT6, GRIA2 and WT-1." (PMID 25884588, 2015).
tumor (continued). "In the present case, the tumour cells were strongly positive for CD34 and Bcl-2, but were negative for CD117, smooth muscle antigen, S-100, EMA and desmin expression, indicating that the tumour was an SFT." (PMID 25663869, 2015). "Immunohistochemical profile of tumor was similar to the first case including strong and diffuse MUC4, vimentin and bcl-2, weak EMA expression except negative immunoreactivity for CD99." (PMID 26449317, 2015). "Thus, ARTD1 might therefore act as a tumor suppressor in absence of BCL2 in ATM wild-type DLBCL." (PMID 26654227, 2015). "Immunohistochemically, tumor cells were diffusely positive for Vimentin and CD99, focal positive for CD34, Bcl-2 and Actin, negative for CK, EMA, Desmin, CD117, GFAP, PR and S-100." (PMID 26155787, 2015). "The tumor cells expressed CD34, bcl-2, CD99, and vimentin and were negative for LCA (leukocyte common antigen), desmin, SMA (smooth muscle antigen), CK7, CK34, BE12, CK19, and CK20." (PMID 25688313, 2015). "On the opposite, BCL-2 and BECLIN 1 were not detectable (by western blotting) in the tumour case 2, and in spite of this the tumour was intensely LC3 positive, which possibly was associated with BECLIN 1-independent autophagy." (PMID 25136588, 2014). "In TN subgroup, women with BCL-2 immunopositive (classes 1 + 2) tumours were characterized by 85.7 % of DFS, whereas those without BCL-2 expression by 38.5 % of DFS." (PMID 25005788, 2014). "By immunohistochemical staining, the tumour cells were positive for CD34, Bcl-2, and SMA and negative for desmin, S100, C-kit, and HMB-45." (PMID 24490095, 2013). "In summary, the positive reactivity of CD34, Bcl-2, and SMA and negative reactivity of C-kit, S100, and desmin of the tumour were compatible with solitary fibrous tumour." (PMID 24490095, 2013). "Immunohistochemistry has shown that non-adipocytic tumor cells are consistently positive for CD99 and, less frequently, for CD34 (75%) and Bcl-2 (60%)." (PMID 24179528, 2013). "In tumor xenografts of SULT2B1-RNAi-LV cells, cyclinB1, MYC and BCL2 protein levels decreased, while no significantly differences in cyclinD1 protein levels was observed between the two groups." (PMID 23593328, 2013). "Immunohistochemically, the tumor cells were strongly positive for CD34, CD99, Bcl-2, and vimentin and negative for smooth muscle actin (SMA), CD31, cytokeratin, S-100, CD117, and epithelial membrane antigen (EMA)." (PMID 21443810, 2011). "With immunohistochemical stains, tumor cells reacted positive for CD34, Bcl-2, and ki67 and negative for CD10, CD117, S100, and Desmin." (PMID 21819590, 2011). "In our case, the tumor cells were strongly positive for CD34, CD99, Bcl-2, and vimentin and negative for smooth muscle actin (SMA), CD31, cytokeratin, S-100, CD117, and epithelial membrane antigen (EMA)." (PMID 21443810, 2011). "The aim of the current study was to prospectively test the clinical validity of BCL2 as a prognostic marker independent of ER, HER2 and adjuvant therapy received, in addition to tumour size, grade and nodal status." (PMID 20664598, 2010). "The prognostic value of BCL2 was present across molecular subtypes (ER+/luminal, HER2+, HER2− and triple negative), an important new observation, and was independent of tumour size, grade and stage." (PMID 20664598, 2010). "We found that increased expression of Bcl-XL, but not Bcl-2, suppressed TRAIL-induced apoptosis in tumour cells." (PMID 12644829, 2003). "Specifically, KLF6, BCL2, ETS1, and PLOD2 could provide insights into tumor biology, hypoxia adaptations, and aggressiveness without invasive biopsies." (PMID 40500522, 2025).